EGF (epidermal growth factor)
Diseases named in the same sentence as EGF in open-access papers (continued):
Sharing a sentence is not in itself a finding about the gene and the disease.
tumor (continued). "Cell-cell communications analysis in scRNA-seq and stRNA-seq identified ligand-receptor pairs of the CXCL, EGF, FGF, and MIF signaling pathways as bridges implying that tumor microenvironment may cause malignant cells’ transcriptomic adaptability and disease progression." (PMID 37397378, 2023). "A high EGF amount plus EGFR overexpression could create conditions for tumor growth, even without specific EGFR mutations." (PMID 36146635, 2022). "CAFs also cause tumour cells to secrete factors that stimulate them, such as hepatocyte growth factor (HGF), connective tissue growth factor (CTGF), epidermal growth factor (EGF), insulin-like growth factor (IGF), nerve growth factor (NGF), FGF, and Wnt family members." (PMID 36555218, 2022). "Thus, a number of tumor cells and CTCs (CD87+, CD87+CD117+, and CD276+CD117+ and Axl+SOX2+, EGF+SOX2+, and CD87+SOX2+) may be interesting as diagnostic markers of SCLC or indicators of dynamic disease control." (PMID 36142766, 2022). "In order to do this, different mechanisms have been proposed: tumour growth can be caused through eosinophil-derived CCL22, by thymic stromal lymphopoietin (TSLP) that induces angiogenesis via VEGFA and by eosinophils-derived epidermal growth factor (EGF) along with TGF-β." (PMID 35406451, 2022). "Noteworthily, a high single IORT dose elicits impact beyond the direct killing of residual tumor cells, because of influencing the microenvironment in the wound fluid through the interruption of the proliferative cytokine cascade and downregulation of the local expression of epidermal growth factor." (PMID 33938966, 2021). "Furthermore, tumor-selective viral replication is enhanced by the deletions of both TK and another gene on the VV genome, which encodes the vaccinia growth factor (VGF) and is the viral analogue of cellular epidermal growth factor (EGF)." (PMID 33922406, 2021). "Likewise, studies focusing solely on visualization of tumor specific molecular markers, amongst these IDH (isocitrate dehydrogenase gene) mutation, EGFR (Epidermal Growth Factor) gene amplification and the proliferation biomarker Ki-67, were not included despite promising results in earlier studies." (PMID 33806195, 2021). "Thus, the activation of EGF/EGFR signalling pathways, together with signals from tumour-associated endothelial cells, facilitate both the EMT process and the enrichment of CSC-like cells with an increased invasiveness, motility, and metastatic potential in vitro and in vivo." (PMID 34831291, 2021). "Moreover, poly(N-(2-hydroxypropyl)methacrylamide)-based copolymers labeled with fluorescent dyes were targeted with the EGFR-binding oligopeptide GE-11 (YHWYGYTPQNVI), human EGF or anti-EGFR monoclonal antibody cetuximab were all able to actively target the surface of EGFR-positive tumor cells." (PMID 31906300, 2020). "Tumor-associated macrophages (TAMs) promote spheroid formation during metastasis of EOC and constitute a central component of spheroid, in which TAMs support tumor cell migration, survive and proliferation by secreting EGF; therefore, TAMs are attractive targets in EOC treatment." (PMID 32477126, 2020). "However, the secreted EGF could have amplified the EGF-dependent anticipatory UPR in residual tumor cells." (PMID 32630838, 2020). "Therefore, the effects of NHWD-870 on CSF1 could affect the ability of the macrophages to proliferate and to secret EGF, which is required for optimal growth of tumor cells." (PMID 32286255, 2020). "Thus, EGF may act as an initiator factor to facilitate the transforming process of tumor cells from low metastatic potential into high metastatic potential, especially by acting on the metabolism of HCC cells." (PMID 32933027, 2020).
tumor (continued). "Several studies illustrate that a substantial part of the clinical responses observed following EGFR targeting treatments may not only be mediated by direct effects on the tumour, but also by regulation of immune responses, an aspect of EGF biology that remains undervalued." (PMID 30659329, 2019). "Moreover, PAX1 significantly inhibited tumor growth in cells pretreated with EGF." (PMID 31235851, 2019). "The reduction in EGFR-mediated function in cultured U87 tumor cells by treatment with the clone 967 plasmid DNA encapsulated within THLs targeted with the HIRMAb was demonstrated by measurement of intracellular calcium flux in these tumor cells treated with the EGF peptide." (PMID 31998120, 2019). "Besides EGF acting as a soluble factor, the increase in EGF-mediated, increased cell–cell contact might also contribute to tumor cell ITGA5 expression through cell-to-cell contact–dependent factors concerning other integrins." (PMID 30710055, 2019). "Moreover, anti-inflammatory TAMs induce S100A8 and S100A9 expression on HCC cancer cells, release CCL22 and epidermal growth factor (EGF) to recruit Treg cells, and promote migration of tumor cells, altogether contributing to HCC malignancy and liver metastasis." (PMID 31611871, 2019). "Finally, the EGF neutralizing antibody attenuated peritoneal tumor burden and increased survival in mice following peritoneal injection of SKOV3-Luc cells and CAFs, accompanied by diminished ITGA5 expression in ATCs and reduced metastases in the anti-EGF treatment group compared with the IgG group." (PMID 30710055, 2019). "Therefore, we next analyzed whether EGF-mediated GLI1 suppression plays a role in modulation of tumor cell motility." (PMID 31867038, 2019). "Increased activation of EGFR at the edges of tumor areas to induce EMT might be fulfilled by cancer-associated fibroblasts, myeloid-derived cells, or, as recently reported, endothelial cells secreting EGF and inducing EMT- and stem-like properties in HNSCCs." (PMID 30261040, 2018). "Interestingly, the combination of treatments induced a prolonged transcriptional activation of nuclear EGFR gene signature compared to individual stimuli (from 2-4 to 8h), indicating that the PGE2 and EGF cooperate in their activities to sustain tumor progression." (PMID 29599917, 2018). "JAK/STAT signaling has been heavily implicated in tumor progression, as have other receptor tyrosine kinases (RTKs), such as those associated with platelet-derived growth factor (PGDF), vascular endothelial growth factor (VEGF), and epidermal growth factor (EGF)." (PMID 30018198, 2018). "GL261 cells were obtained from the NCI-Frederick Cancer Research Tumor Repository and cultured as adherent cells or induced to form neurospheres by placing freshly trypsinized cells into serum-free media containing fibroblast growth factor 2, epidermal growth factor, and B-27 supplement." (PMID 28768483, 2017). "Furthermore, hypoxia can lead to increased metastasis, at least in certain tumor cell types, thus inhibiting the EGF/EGFR/arginase II pathway may also potentially have an additional benefit in limiting metastasis." (PMID 28330951, 2017). "We also observed that hornerin expression increases in HUVECs in response to EGF stimulation, suggesting that one potential mechanism of elevated hornerin in the tumor endothelium is due to tumor cell-derived EGF, however these results remain to be explored in the tumor setting." (PMID 28916756, 2017). "This Nb (referred to as CONAN-1) could inhibit the cell proliferation that depended on EGF in vitro and it could also inhibit the tumor outgrowth with an almost similar potency as the entire Cetuximab mAb and it was more potent than the bivalent, mono-specific Nbs." (PMID 29276515, 2017).
tumor (continued). "However, transwell analysis showed invasion induced by EGF was attenuated by overexpression of PP1 in HCT116 cells to a lesser extent compared with that effect from MIIP S303A, suggesting the additional function of PP1 is implicated in tumor cell invasion." (PMID 29038521, 2017). "Isoform selective PI3K p110δ and Hck inhibitors are available and may be deployed to prevent the activation of tumor invasion by co-migrating TAMs, which not only provide EGF to stimulate tumor cell motility, but also dig tunnels into the surrounding matrix through which tumor cells can escape." (PMID 28629162, 2017). "Therefore, EGF-dose-dependence of the pY1068/EGFR ratio measured using a 10-min stimulation of cells in vitro was employed as a linear standard to estimate ligand concentrations in vivo in tumor xenografts." (PMID 29268862, 2017). "After testing a number of different culture conditions it was shown that CTCs could be propagated in vitro only if they were cultured in hypoxic conditions, as tumor spheres in serum-free media supplemented with epidermal growth factor (EGF), B27 and basic fibroblast growth factor (FGF2)." (PMID 27457474, 2016). "However, antibody treated tumor cells showed significantly increased levels of EGF, which may induce EMT." (PMID 27174921, 2016). "When conjugated to metallic nanoparticles, EGF promotes a rapid internalization into cancer cells, and cancer destruction can be achieved by injecting the light-absorbing nanoparticles locally and applying the laser-mediated hyperthermia directly into the tumour." (PMID 27788212, 2016). "Thus, it is conceivable that some of EGF actions could result from the activation of PRLR by endogenous prolactin expressed in tumor cells." (PMID 27564112, 2016). "Thus, we further tested the possibility that the metastatic process enhanced by EGF-induced COX-2 might occur via regulation of the interaction between tumor and endothelial cells." (PMID 25595899, 2015). "Interestingly, decreased numbers of G1 phase cells were observed in SHG-139S, while the rate of G2 phase cells was increased, compared with the values obtained for SHG-139 cells; these differences were likely related to the effects of bFGF and EGF on tumor cells." (PMID 25879429, 2015). "Tumour microenvironment plays a major role in this process, as both infiltrating and tumour cells produce a range of soluble mediators with protumour activity (e.g. interleukin-6, transforming growth factor β, epidermal growth factor and its receptor, vascular endothelial growth factor, etc.)." (PMID 26626416, 2015). "In addition, to study whether EGF-induced PTX3 regulated the distal dissemination of tumor cells, EGF-treated parental and shPTX3 cells were injected into the tail vein of mice." (PMID 25797258, 2015). "Thus, TME at primary site increases tumor dispersion via paracrine signals by generating a chemotactic relay system, a case that can be further exemplified by CXCL14 secreted by CAFs, or EGF and CXCL5 released by tumor-associated dendritic cells in prostate and lung tumors, respectively." (PMID 25857315, 2015). "Thus, we speculate that EGF-induced PTX3 promoted tumor metastasis by modulating adhesion between tumor and endothelial cells." (PMID 25797258, 2015). "In addition, EGF-induced PTX3 also enhanced tumor cell-endothelial cell interactions." (PMID 25797258, 2015). "Moreover, among the EGF tumour specific proteins n = 11 were likewise uniquely expressed in human HCC and for n = 49 proteins regulation in human HCC was confirmed using the publically available Human Protein Atlas depository, therefore demonstrating clinical significance." (PMID 25872475, 2015). "This small leucine-rich proteoglycan may inhibit tumor cell growth, migration, angiogenesis and metastasis by interaction with different receptor tyrosine kinases such as EGF, other erbB family members, c-Met and IGF-1R and upregulation of p21WAF1/CIP1 (p21) via a p-53 independent pathway." (PMID 26437222, 2015).
tumor (continued). "Therefore, reduction of VCAM-1 and EGF by combination treatment might have favorable effects in terms of inhibition of tumor cell invasion and tumor immune evasion." (PMID 25030093, 2014). "Cell therapy could be a potential method to deliver drugs, such as anti-EGF to tumor cells." (PMID 24675463, 2014). "CCSCs may be expanded as tumor spheres in vitro using a serum-free medium containing EGF and bFGF." (PMID 24944672, 2014). "On the other hand, preceding studies have indicated that exacerbated signaling of multiple members of the EGF-R family often causes uncontrolled proliferation of cancer cells, which might justify the reason why the tumor became resistant at 28 days, when the levels of EGF/EGF-R were higher." (PMID 25549350, 2014). "However, a recent study showed that transfection of TRβ1 into human SK-hep1 cells reduced HCC xenograft tumor growth in nude mice, promoted partial mesenchymal-to-epithelial transition, attenuated tumor cell invasiveness, and blocked tumor cell responses to growth factors EGF, IGF-1, and TGF-β." (PMID 23924944, 2013). "PDT induced a rapid but rather transient phosphorylation of eIF2α, which was slightly attenuated after incubation of tumor cells with EGF-SubA, suggesting that restoration of translation by the cytotoxin may contribute to potentiation of the cytotoxic effect of PDT." (PMID 23887632, 2013). "Moreover, these compounds may delay and decrease the action of such factors of carcinogenesis as some tumor promoters (EGF, phorbol esters), defend against UV radiation and inhibit the tumor invasion by modulation of metalloproteinases." (PMID 24317475, 2013). "EGF signalling is not only capable of potent mitogenic and tumourigenic effects, but also stimulates angiogenesis in human solid tumours, through direct effects upon the endothelium of new vessels, or indirectly by altering expression of positive and negative regulators of angiogenesis by tumours." (PMID 24180698, 2013). "The administration of EGF may lead to an increased tumor cell motility." (PMID 22825751, 2012). "It is hypothesized that EGF application increases tumor cell invasiveness." (PMID 22825751, 2012). "Likewise, the antiestrogen ICI 164,384 reduced the effects of EGF-induced tumor proliferation." (PMID 22164169, 2011). "Notably, components of the EGF signaling network, Adam10, a metallopeptidase that processes EGF, and Grb2, an adaptor protein that binds directly to the EGF receptor, exhibited a greater importance for transgenic than for tumor TFs (blue dots)." (PMID 21464922, 2011). "Interestingly, the mitogenic EGF suppressed both CysLT2R mRNA and protein expression as well as the promoter activity, strengthening the hypothesis that the CysLT2R is a potential tumor suppressor." (PMID 22194989, 2011). "Hence, our goal was to identify EGF-dependent transcription regulators that could exert the switch from the transgenic to the tumor state." (PMID 21464922, 2011). "In a typical tumour sphere assay, cells from a primary tumour or cancer cell line are dissociated into a single cell suspension and cultured in a serum-free growth factor-rich medium containing primarily epidermal growth factor (EGF) and fibroblast growth factor (FGF)." (PMID 21318146, 2010). "Moreover, it may explain that peripheral tumor cells receive a signal from EGF resulting in the proliferation of cancerous tissues." (PMID 20579333, 2010). "Moreover, because cell surface clustering of a variety of receptors, including EGFR, has been shown to augment receptor function, we hypothesized that α6β4 integrin-induced EGFR clustering might augment particular tumor cell responses to EGF." (PMID 19470173, 2009). "However, several experimental findings have supported a role for macrophages in enhancing tumour progression through production of growth and angiogenic factors including the epidermal growth factor, transforming growth factor-β, and vascular endothelial growth factor." (PMID 18283317, 2008).
tumor (continued). "Exploring a combination of VDAs and epidermal growth factor receptor (EGFR) inhibitors theoretically could also be an interesting approach; here one could speculate that tumour cells in the viable rim will become apoptotic and die when being deprived of their growth-stimulating factors such as EGF." (PMID 17375046, 2007). "It was postulated that some tumours may produce high levels of EGFR ligands (TGF-α, EGF), thus stimulating EGFR expression in tumour-associated endothelial cells and setting up a paracrine endothelial cell survival signalling pathway that is sensitive to inhibitors of EGFR signalling." (PMID 15928657, 2005). "Thus this model may well represent a new strategy to ameliorate the chemotherapy of EGF-dependent refractory tumours." (PMID 15365562, 2004). "However, HMECs secreted in response to EGF, 5–10 fold more AR than tumour cells." (PMID 11286474, 2001). "Simultaneously, M2 TAMs promote angiogenesis by secreting an abundance of growth factors and pro-angiogenic cytokines (EGF, PDGF, TGF-β, FGF, IL-8) that feed the growing tumor and collectively promote malignancy." (PMID 41597210, 2026). "IL6/IL6R/STAT3 and HIF1α/ZEB1 pathways induce epithelial to mesenchymal transition (EMT) and CAFs secrete EGF, FGF and HGF for tumour growth." (PMID 41476776, 2026). "These interactions were enriched in growth factor- and cytokine-mediated pathways, including TGFB1-TGFBR2, IL6-IL6R, and EGF-EGFR signaling, suggesting that AP1AR upregulation amplifies paracrine networks supporting tumor proliferation and immune remodeling." (PMID 41438582, 2026). "EGF activates the ERK-MAPK pathway, leading to phosphorylation of SAM68, which regulates the alternative splicing of CD44, a key mediator of tumor progression." (PMID 41584352, 2026). "Epidermal growth factor (EGF), predominantly secreted by CD206+ TAMs, promotes the invasion and mobility of CRC cells, and activation of EGFR on tumor cells is required for sustained intravasation." (PMID 41438574, 2026). "Compared to Lipo-DOX, a widely used clinical formulation of liposomal DOX in China, EGF-Exo-DOX demonstrates superior cellular uptake, greater induction of tumor cell apoptosis, and improved anti-tumor efficacy." (PMID 41593600, 2026). "TGF-β′s tumour suppressing effects are abrogated by interaction with inflammatory pathways including platelet derived growth factor (PDGF), and EGF autocrine loops, which enable immune evasion and metastatic spread." (PMID 41476776, 2026). "Our studies have demonstrated that SOX11 is upregulated by the EGF-EGFR-STAT3 signaling pathway and subsequently activates EMT-TFs, facilitating EMT and tumor progression." (PMID 41511366, 2026). "This aligns with evidence that high APOC1 expression enhances the secretion of cytokines, such as EGF, PDGF, VEGFA, IL-1, IL-8, TNF-α, MMP-9, MMP-2, and NO, which collectively drive tumor cell proliferation, invasion, and angiogenesis." (PMID 39873475, 2025). "The epidermal growth factor (EGF) and VEGF, whose role has already been discussed in this paper, represent a target of research because of their hyper-expression in the tumor site." (PMID 40944840, 2025). "Research has demonstrated that TAMs contribute to tumor angiogenesis by secreting various pro-angiogenic factors, including VEGF-A, epidermal growth factor (EGF), TNF-α, and CXCL12." (PMID 40599798, 2025). "Epidermal growth factor (EGF) and vascular endothelial growth factor (VEGF) are proven crucial components that regulate the proliferation and dissemination of tumor cells." (PMID 41155569, 2025). "Beyond immunosuppression, LAMs promote tumor growth through secretion of vascular endothelial growth factor (VEGF) and epidermal growth factor (EGF), supporting angiogenesis, extracellular matrix remodeling, and recruitment of additional stromal elements." (PMID 41303704, 2025). "The differentially expressed cytokines between tumor-bearing and tumor-free mice included CSF2, TGFB1, IL33, IL1B, and EGF." (PMID 41214328, 2025).